CD4 (CD4 molecule)
Diseases named in the same sentence as CD4 in open-access papers (continued):
Sharing a sentence is not in itself a finding about the gene and the disease.
HIV-1 infection (continued). "In this CD4-independent HIV-1 infection, GalCer or other sphingolipids could act as co-factors to induce structural modifications of HIV-1 glycoprotein, thus catalyzing the interaction with CCR5 and promoting viral entry." (PMID 37511488, 2023). "Finally, we observed that ML-NK cells also detected the presence of HIV-1 infection in CD4+ T cells, potentially decreasing HIV viral protein expression." (PMID 37865647, 2023). "Knowing that this post-translational modification regulates ORP3 binding to VAP-A and Rab738,57, the absence of ORP3 hyperphosphorylation may explain, at least in part, the resistance of quiescent CD4+ T cells to HIV-1 infection." (PMID 37563144, 2023). "HIV-1 infection in memory CD4+ T cells forms a latent reservoir that is a barrier to cure." (PMID 37033916, 2023). "Similarly, GBP2 and GBP5 are two guanylate binding proteins known to restrict HIV-1 entry and previously shown to be transcribed from LTR12C elements upon HIV-1 infection of primary CD4+ T cells." (PMID 38168352, 2023). "The contribution of HLA-DR+ CD4+ T cells to HIV-1 persistence was highlighted in recent studies in adults showing higher levels of HIV-1 infection in HLA-DR+ cells compared with HLA-DR- memory CD4+ T cells during prolonged ART, along with higher proportions of intact HIV-1 DNA." (PMID 37033916, 2023). "Clusters of mature HIV-1 particles resembling biofilms were also detected at the surface of infected MOLT cells (human acute lymphoblastic leukemia, T-cells), at the surface of primary CD4(+) T-cells upon in vitro HIV-1 infection, and at the surface of CD4(+) T-cells from HIV-1-infected patients." (PMID 37889017, 2023). "In strong contrast, activation of DCs by lipopolysaccharide (LPS) or interferon (IFN), which are immunomodulatory signals present during HIV-1 infection, diminishes their susceptibility to infection but significantly increases the capture of HIV-1 and enhances the trans-infection of CD4+ T cells." (PMID 36940134, 2023). "Consistent with this hypothesis, recent publications show that HIV-1 infection drives CARD8-dependent pyroptotic cell death both in primary human CD4+ T cells ex vivo and in humanized mouse models of HIV-1." (PMID 37417868, 2023). "Finally, additional studies show that the early steps of HIV-1 infection, such as virus binding to CD4 or membrane fusion, allow the virus to increase the autophagocytic pathway, hence preparing the cells to be more permissive to viral infection." (PMID 37446195, 2023). "Since the Fas/FasL pathway is involved in memory CD4+ T cell death in HIV-1 infection, we next assessed whether the IRF-5–CPP mix could block Fas-mediated apoptosis in memory CD4+ T cells from ART HIV-1+ individuals." (PMID 37227774, 2023). "HIV-1 infection is characterized by inflammation and a progressive decline in CD4+ T cell count." (PMID 37227774, 2023). "TLR7 is known to be expressed in human CD4+ T cells during HIV-1 infection, but it is still unknown whether TLR7 expression is maintained in CD4+ T cells after ART." (PMID 37227774, 2023). "HIV-1 infection was reported to lead to Caspase-1-mediated pyroptosis in most CD4 T cells." (PMID 38132483, 2023). "This mimics aspects of a physiological route of acute CNS HIV-1 infection in people, where peripheral CD4+ T-cells or monocytes are the initial HIV-1 targets that are then trafficked to the brain to infect microglial cells, which are the primary resident HIV-1 target in the CNS." (PMID 38032195, 2023). "CD4+ T cell decline is a common way to measure the virulence of a HIV-1 infection." (PMID 37161335, 2023). "The 3D model has reciprocated the motility of CD4+ T cells reduces upon HIV-1 infection." (PMID 37215829, 2023). "During HIV-1 infection, there are conflicting reports that mast cells may act as reservoirs of latent infection and also promote viral trans-infection of CD4+ T cells." (PMID 37371943, 2023).
HIV-1 infection (continued). "A sharp decrease in the plasma levels of IL-17 could have been associated with the decrease in the population of IL-17-secreting (Th17) CD4+ T-cells characteristic of both TB and HIV-1 infections." (PMID 37376629, 2023). "IP-10 and I-TAC have been shown to be correlated with HIV-1 severity in humans as monocytes and dendritic cells (DCs) produce IP-10 in response to HIV-1 infection and promote latent infection in resting memory CD4 T cells by facilitating HIV entry and integration (31, –, 33)." (PMID 37874153, 2023). "In addition, pyroptosis has been found to drive CD4+ T-cell depletion and chronic inflammation in HIV-1 infection." (PMID 37486928, 2023). "TGF-β1 might also induce apoptosis of CD4+ T lymphocytes following macrophage-tropic (R5) HIV-1 infection, by reducing levels of anti-apoptotic factors as well as by increasing apoptosis-inducing factors." (PMID 36563749, 2023). "Moreover, the inability of antiretrovirals to access latent reservoirs, characterized by infected long-lived memory CD4+ T lymphocytes and macrophages, results in the persistent immune activation and inflammation observed in the course of HIV-1 infection." (PMID 37646023, 2023). "HIV-1 infection of resting CD4+ T cells is inefficient compared to infection of activated cells." (PMID 37515158, 2023). "Despite effective antiretroviral therapy (ART), a reservoir of latent, replication-competent proviral HIV-1 DNA persists in resting CD4+ T cells and potentially other cell types such as myeloid cells, which represents a major barrier to either a sterilizing or functional cure for HIV-1 infection." (PMID 36671485, 2023). "Early after HIV-1 infection, lamina propria CD4+ T cells are drastically reduced, triggering a cascade of events leading to gut dysbiosis, reducing the abundance of beneficial gut symbionts, and causing the disruption of the intestinal epithelium’s tight junctions." (PMID 36853052, 2023). "In the context of HIV-1 infection, IFNα can act to restrict virus replication, promote viral latency, contribute to chronic inflammation, and/or exert cytostatic effects leading to the gradual decline of CD4+ T cells." (PMID 37112874, 2023). "On the other hand, it promotes HIV-1 infection by increasing the availability of CCR5+CD4+ T cells." (PMID 36821374, 2023). "HIV screening revealed a previously unknown HIV-1 infection, with a CD4 cell count of 216 cell/μL and viral load of 361.000 copies/mL at diagnosis." (PMID 36086677, 2022). "Macrophages are an early cellular target for the HIV-1 infection, and the transmission between humans is caused by the macrophage-tropic virus rather than the CD4+ T cell-tropic virus." (PMID 35746791, 2022). "As SPHK inhibition, in addition to S1PR modulation with FTY720, hinders HIV-1 cell-to-cell transmission, our results suggest that SPHK1 and SPHK2 are involved in HIV-1 infection of primary CD4 T cells and represent unique targets toward halting HIV-1 infection." (PMID 35412343, 2022). "In this work, we examined whether targeting SPHK to reduce conversion of sphingosine to S1P could alter the course of HIV-1 infection in primary CD4 T cells." (PMID 35412343, 2022). "However, an early study showed that the ADE of HIV-1 infection proceeding via FcγRI required the virus glycoprotein interaction with its cell surface receptor, the CD4 molecule." (PMID 36136686, 2022). "Furthermore, Clerc and colleagues demonstrated that glutaminolysis is the major pathway fueling the tricarboxylic acid cycle and OXPHOS in T-cell receptor-stimulated naïve and memory CD4 subsets, and is required for optimal HIV-1 infection." (PMID 36016435, 2022). "Moreover, the effect of IFN-α in promoting HIV-1 infection is observed not only in Jurkat cells but also in SupT11 cells, another human CD4+ T cell line, suggesting that this enhancing effect is not specific for this cell line." (PMID 35468127, 2022).
HIV-1 infection (continued). "In this study, the majority of CD4 T cell death (~95%) occurred in uninfected bystander cells, and pyroptosis was induced via innate immune sensing of incomplete reverse transcription products accumulated during abortive HIV-1 infection." (PMID 36000842, 2022). "Finally, we applied this technology to a primary CD4+ T cell model of early HIV-1 infection to identify genes that directly contribute to sensitivity or resistance to HIV-1 infection." (PMID 36175869, 2022). "HTLV-1 virions and proteins upregulate HIV-1 infection by activating CD4+ T cells." (PMID 36146843, 2022). "To apply the KI approach to a functional analysis in the context of HIV-1 infection in resting CD4+ T cells, we introduced the eGFP gene upstream of the SAMHD1 locus to generate a GFP-SAMHD1 fusion protein, which is a Vpx-degradable and enzymatically active analog of non-tagged SAMHD1." (PMID 34949807, 2022). "During HIV-1 infection, the metabolic activity of the cell together with glycolytic enzymes and activation stage regulates susceptibility to HIV-1 where elevated OXPHOS and glycolysis favors infection in CD4+ T cells." (PMID 35005552, 2022). "Existing research heavily emphasizes the role of macrophages and CD4+ T cells in HIV-1 infections." (PMID 36146843, 2022). "A recent study has suggested that alterations in CD4 cell concentrations may control HIV-1 infections and disease progression." (PMID 36380676, 2022). "HIV-1 infection has been shown to induce (macrophages) or inhibit (CD4 + T cells) autophagy." (PMID 36403071, 2022). "TREX1 downregulates the synthesis of IFN triggered by HIV-1 infection in both CD4+ T cells and macrophages; HIV-1 DNA accumulates in the cytoplasm in cells in which TREX1 is inhibited by RNA-mediated interference, although a modest induction of IFN-induced genes (ISG) can be observed upon infection." (PMID 35328442, 2022). "Collectively, the circulating CD4+ T cells and development of CD4+ T cell-rich lymphoid tissues suggest that the TKO hu-PBMC model may facilitate in vivo studies of HIV-1 infection." (PMID 34818071, 2022). "In early HIV-1 infection, when CD4 T cell levels remain elevated, but CD4 T-cell function begins to be compromised, patients may develop BL." (PMID 35894054, 2022). "Overall, we demonstrate that GZB+ CD4 T cells are prevalent in the colon during chronic HIV-1 infection and may emerge following interactions with translocated bacteria in an IL-2 and MHC Class II-dependent manner." (PMID 35258402, 2022). "In HIV infected patients, TCRαβ+ DNT cells were thought to be derived both normally from within the thymus, and also from cells originally expressing CD4, but which have undergone CD4 downregulation in response to HIV-1 infection through the cooperative action of Env, Nef, and Vpu." (PMID 36443691, 2022). "A recent study demonstrated that two mitochondria-localized proteins (NLRX1 and FASTKD5) mediate OxPhos upregulation during HIV-1 infection of CD4+ T cells, promoting viral replication, thus uncovering a novel and interesting regulatory axis for therapeutic targeting against HIV-1 infection." (PMID 35205318, 2022). "Next, we investigated whether endogenous BST-2 mRNA expression levels in PBMCs translated to BST-2 protein expression levels on the surface of CD4+ T cells, the main target cells of HIV-1 infection in vivo." (PMID 35081977, 2022). "Therefore, the degree of permissivity to HIV-1 infection of these CD4+ T cells appears to be dependent on the level of TDP-43 which conditions the expression level of the antiviral HDAC6 enzyme and MT acetylation in α-tubulin." (PMID 35682862, 2022). "The problem is complex, since as soon as HIV-1 infection initiates, reservoirs may also establish within resting memory CD4+ T cells and other cells." (PMID 35215997, 2022).
HIV-1 infection (continued). "Pre-treatment with PC liposomes significantly inhibited the luciferase activity in macrophages infected with HIV-1 (Ba-L Env) but not in those infected with HIV-1 (VSV-G), indicating that PC liposome-mediated CD4 downregulation reduced HIV-1 infection in type-1 macrophages at entry level." (PMID 35663973, 2022). "The mechanisms underlying depletion of CD4 T cells during acute HIV-1 infection are not well understood." (PMID 36000842, 2022). "As anticipated, 2P23-iMab could bind to the cell membrane through CD4 anchoring and inhibit HIV-1 infection as well as viral Env-mediated cell–cell fusion efficiently." (PMID 35711654, 2022). "Our results indicate that CD98high CD4+ T cells are hyper-permissive for HIV-1 infection." (PMID 36214569, 2022). "Thus, we evaluated the antiviral activity of selective JAK2i fedratinib and AZD1480, and the pan-JAKi ruxolitinib, in acute HIV-1 infection in primary CD4+T cells from healthy donors (n=3)." (PMID 36131914, 2022). "Indeed, two interesting changes among MSM cases were also observed: steadily increasing proportion of CD4hi cases (CD4 count >500 cells/μl) and continuously rising rate of recent HIV-1 infections." (PMID 36504809, 2022). "Sphingosine kinase or S1P receptor inhibition reduce HIV-1 infection in primary CD4 T cells." (PMID 35412343, 2022). "The CD98high CD4+ T cells are highly permissive for HIV-1 infection." (PMID 36214569, 2022). "Since Gal-1 profoundly influences CD4+ T cell functionality and macrophages are an important source of this lectin, we investigated the interplay between macrophage activation and Gal-1 secretion during HIV-1 infection and its impact on latently infected CD4+ T cells." (PMID 35943163, 2022). "The use of a CD4+ T-cell line is important in order to accurately represent the cellular tropism of HIV-1 infection in vivo, reasoning that Env trafficking may be altered in Env cytoplasmic tail-dependent versus -independent cell lines." (PMID 35770989, 2022). "Additionally, the density-dependent effect of IFN-α in promoting HIV-1 infection was observed in primary human CD4+ T cells from two different donors." (PMID 35468127, 2022). "As such, we targeted the expression of five genes with roles in HIV-1 infection (CD4, CXCR4, PSGL-1, TRIM5α and CPSF6) as well as CD46, in part using gRNAs pre-tested for each target for the efficiency of editing and protein loss was assessed in part by confocal microscopy." (PMID 34949807, 2022). "We therefore hypothesized that limiting the availability of S1P itself would hinder HIV-1 infection in CD4 T cells." (PMID 35412343, 2022). "Indeed, a link between excessive uptake of glucose by CD4+ T cells has been shown to induce hyper-immune activation in the context of HIV-1 infection." (PMID 36203587, 2022). "However, astrocytes can undergo other means of HIV-1 infection such as direct cell-cell transfer of the virus via infected CD4+ T cells, whose trafficking into the CNS has been established." (PMID 35784841, 2022). "This could mean that during HIV-1 infection, Tregs might be preserved within the total CD4 T cells compartment." (PMID 35287587, 2022). "Thus, these cells are less permissive to HIV-1 infection, as compared to activated CD4+ T-cells due to host restriction factors which limit the HIV-1 infection." (PMID 34697376, 2021). "Briefly, immunodeficient mice (such as nonobese diabetic–SCID common γ–/– (NSG) neonatal mice) were engrafted with human fetal liver CD34+ hematopoietic stem and progenitor cells to establish human CD4+ T cells in mice that allowed for HIV-1 infection in the peripheral blood and tissues." (PMID 34578439, 2021). "It has been shown that hBD-2 and/or hBD-3 may inhibit HIV-1 infection of CD4 T lymphocytes and macrophages." (PMID 34696473, 2021). "HIV-1 infection of CD4+ T cells significantly helps the life-long persistence of the virus." (PMID 34578439, 2021).
HIV-1 infection (continued). "Approximately 20% of people with HIV-1 infection who commence ART with severe CD4+ T cell depletion (CD4+ T cell count <100/μL) experience an IRIS during the first 3 months of ART associated with a treated or unrecognized infection by various opportunistic pathogens." (PMID 33841434, 2021). "The first HIV-positive samples were collected individually at 12~97 days post infection (dpi); 31 of the 54 (57.4%) participants experienced a precipitous drop in the CD4+ T cell count during the 2-year observation period after HIV-1 infection, and 16 consented to start ART." (PMID 34804062, 2021). "Then early activation of TIGIT+NK and TIGIT−NK cells may lead to the depletion of CD4 T cells in acute and chronic HIV-1 infection, especially in the first month of infection (TIGIT+NK: r = −0.72, P = 0.001; TIGIT−NK: r = −0.66, P = 0.004)." (PMID 33717085, 2021). "Indeed, autophagy-targeting drugs have already proved effective in intervening in HIV-1 infection in human macrophages, DCs, PBMCs, and CD4+ T cells." (PMID 33669846, 2021). "Further studies designed to separate platelet-CD4+ T cell aggregates ex vivo may provide insights into the mechanisms of platelet-CD4+ T cell aggregate permissiveness and disease progression in HIV-1 infection." (PMID 34987521, 2021). "Importantly, when HIV-1 infected the primary CD4+ T lymphocytes, the expression level of FKBP3 in these cells increased significantly, suggesting a possible involvement in the immune response of CD4+ T lymphocytes to HIV-1 infection." (PMID 34281390, 2021). "Moreover, the early production of the chemokines CCL3 and CCL4 has been shown to exacerbate HIV-1 infection by recruiting target CD4+ T cells to the infection foci." (PMID 34198973, 2021). "Platelet-CD4+ T cell aggregate formation was increased during HIV-1 infection." (PMID 34987521, 2021). "The presence of platelet-CD4+ T cell aggregates in lymph nodes may be mediated by activated platelets, contributing to the antiviral role of T cells in the lymph nodes during HIV-1 infection." (PMID 34987521, 2021). "As early as during primary HIV-1 infection, HIV-1 integration events are found to occur in RIGs, genes associated with clonal expansion of latently HIV-1–infected CD4+ T cells, and cancer-related and highly expressed genes in both resting and activated CD4+ T cells." (PMID 33784259, 2021). "Furthermore, chimera treatments prevented HIV-1-induced depletion of helper CD4+ T cells, a significant characteristic of HIV-1 infection at the acute stage." (PMID 34858370, 2021). "How the latent HIV-1 infection pool in the memory CD4+ T cell population remains stable despite the expected and likely required exposure of latently HIV-1 infected T cells to their cognate antigen, and the resulting potent biological activation of the host T cells, has not been detailed." (PMID 33465149, 2021). "It is also possible that hBD-2PTD and/or hBD-3PTD may inhibit HIV-1 infection in CD4+ T lymphocytes, CD68+ macrophages, and CD1c+ DC in the tonsil tissue." (PMID 34696473, 2021). "The half-life of individual CD4+ central memory T cells (TCM cells) that are thought to serve as host cells of latent HIV-1 infection events ranges between 20 and ~100 days and is generally shorter in HIV patients than in healthy individuals, with most studies suggesting a half-life τ1/2 <50 days." (PMID 33465149, 2021). "We reasoned that CD73+ memory CD4+ T cells decrease very early in HIV-1 infection." (PMID 33477692, 2021). "Interestingly, in the same study the protective effect of estradiol against HIV-1 infection was more pronounced in macrophages than in CD4+ T cells." (PMID 33594113, 2021). "Knowing the mechanisms that govern the persistence of infected CD4+ subpopulations could help us to design new therapies to cure HIV-1 infection." (PMID 34844430, 2021).